CXCL17 (C-X-C motif chemokine ligand 17)
Diseases named in the same sentence as CXCL17 in open-access papers (continued):
Sharing a sentence is not in itself a finding about the gene and the disease.
tumor (continued). "The correlations between the mRNA expression levels of CXCL14, CXCL16, and CXCL17 in the primary tumor tissues were assessed by a two-tailed Spearman’s rank order correlation test." (PMID 31752131, 2019). "Recently, we showed that CXCL17 is ectopically expressed in tumor cells and in metastatic tumors of regional lymph nodes of colon cancer (CC) patients." (PMID 31752131, 2019). "CXCL17 is a latest member of the C-X-C chemokine family proteins and aberrant expression of it promotes tumour progression through angiogenesis." (PMID 28330331, 2016). "Patients with less CXCL17+ cells within the tumor had significantly prolonged OS and RFS compared with the CXCL17high subgroup." (PMID 25303284, 2014). "In conclusion, we demonstrate for the first time that CXCL17 is mainly produced by tumor-infiltrating neutrophils and that it can be used as an independent indicator of poor prognosis for both OS and RFS in HCC." (PMID 25303284, 2014). "CXCL17 signals were mainly located in the cytoplasm of stromal cells, but were also observed occasionally in the cytoplasm or nuclei of tumor cells." (PMID 25303284, 2014). "Our results provide the first evidence that tumor-infiltrating CXCL17+ cell density is an independent prognostic factor that predicts both OS and RFS in HCC." (PMID 25303284, 2014). "CXCL17 is a chemokine involved in tumor angiogenesis and is an anti-inflammatory factor that we have also observed to be over-expressed in mustard lung." (PMID 24978043, 2014). "The CXCL17 expression was a significant predictor of unfavorable RFS and OS in HCC patients, implying that CXCL17 functions as a pro-tumor factor in HCC." (PMID 25303284, 2014). "CXCL17 expression by tumor cells was reported to recruit CD11b+Gr1highF4/80− neutrophilic myeloid-derived suppressor cells." (PMID 25303284, 2014). "When stratified by tumor multiplicity, the peritumoral CXCL17 density remained a good predictor of OS (all P<0.05)." (PMID 25303284, 2014). "By using multiple immunofluorescence staining we revealed that CXCL17 was mainly expressed by stromal cells in the peritumoral region, while tumor cells expressed CXCL17 with lower intensity." (PMID 25303284, 2014). "Our studies support the view that the aberrant expression of CXCL17 in human cancer cells recruits immature myeloid-derived cells in mice and promotes tumor progression through angiogenesis." (PMID 22952881, 2012). "While CXCL17 was identified as a potential chemokine to human immature DCs and monocytes, it has been shown to act as a tumor-forming factor." (PMID 22952881, 2012). "The analyzed imaging data correlated well with the CD31-positivity in specimens of CXCL17-expressing tumors, suggesting that CXCL17-mediated tumorigenicity is based on the host-tumor interaction and angiogenesis." (PMID 22952881, 2012). "In an effort to examine tumor angiogenesis through CXCL17, we observed cell infiltrates at the edge of CXCL17-DLD-1-transplanted tumors." (PMID 22952881, 2012). "Herein, we demonstrate that CXCL17 recruits CD11b+Gr1+ myeloid-derived cells at tumor sites and promotes angiogenesis and tumorigenesis." (PMID 22952881, 2012). "Further understanding of the properties of CXCL17 expression and homing cells should provide important clues in efforts to elucidate the components of the tumor microenvironment." (PMID 22952881, 2012). "In this study, we report that the latest member of the C-X-C-type chemokines, CXCL17 (DMC/VCC-1), recruits immature myeloid-derived cells and enhances early tumor progression." (PMID 22952881, 2012). "Overexpression of CXCL17 clearly increased the number of CD11b+Gr-1+ myeloid-derived cells at tumor sites and was coupled with enhanced tumorigenicity and increased vasculature in vivo." (PMID 22952881, 2012). "Similar increases in CXCL17-responding cells were also observed in tumor-bearing BALB/c mice in which CD11b+Gr-1+ accumulated greatly by the transplantation of unmanipulated Colon26 cells." (PMID 22952881, 2012).
tumor (continued). "Moreover, CXCL17 levels in tumor center was correlated significantly with preoperative neutrophil-to-lymphocyte ratio (NLR) and postoperative lymphocyte-to-monocyte ratio (LMR)." (PMID 42255223, 2026). "CXCL17 can both support and suppress tumor growth in certain types of cancer." (PMID 38384293, 2024). "In addition to contributing to the immune response, CXCL17 affects cellular migration which is the onset of diseases such as inflammation and tumor metastasis." (PMID 38384293, 2024). "CXCL17 has the ability to both support and suppress tumor growth in certain types of cancer." (PMID 38384293, 2024). "Since FOXQ1 and THBS2 were ectopically expressed in CC tumor cells it was of interest to compare their expression with other ectopically expressed biomarkers like the chemokines CXCL16 and CXCL17 particularly since these two chemokines were associated with bad prognosis." (PMID 38156105, 2023). "In addition, we found significant upregulation of the CXCL13, XCL2, and CXCL17 genes in samples with TLS infiltration in the tumor." (PMID 36776859, 2023). "Moreover, our study suggested that the low expression of CXCL17 was significantly correlated with a deeper invasive extent, more frequent infiltrative growth patterns of GC, and larger tumor volumes (as indicated by the maximum diameter)." (PMID 36614059, 2022). "In addition, Cxcl15 and Cxcl17 levels were enriched in the NHRI-8-B4 tumor tissues as well as in NHRI-8-B4 cells." (PMID 35721518, 2022). "It has been shown that the function of CXCL17 differs among distinct tumor types." (PMID 36614059, 2022). "CXCL17 was preferentially expressed in the aggressive types of breast, lung and gastrointestinal cancer cells, resulted in the accumulation of immature CD11b+Gr1+ myeloid-derived suppressor cells at tumor sites." (PMID 31620367, 2019). "Furthermore, PDGFR inhibitor imatinib decreased metastatic foci and decreased tumor sizes in the lungs of mice, when compared with isotype-treated and CXCL17 pre-treated mice." (PMID 30755260, 2019). "Other chemokines, for example, CCL7, CCL20, CXCL1, and CXCL17, demonstrate similar expression patterns and may also be important contributors to MØ tumor infiltration, MØ differentiation, and a more aggressive phenotype." (PMID 30451357, 2019). "Meanwhile, CXCL17 acts as a chemo- attractant for monocytes and macrophages, which suggested that it could play an important role in the angiogenesis of tumor development." (PMID 31934638, 2019). "CXCL17 has also been reported to have potential tumour suppressor activity." (PMID 28330331, 2016). "Several studies have proposed that CXCL17 might act as a chemokine that accelerates tumor progression." (PMID 25303284, 2014). "Multivariate analysis showed that tumor-infiltrating CXCL17 could also serve as a new biomarker for predicting HCC prognosis." (PMID 25303284, 2014). "We also tried to find out whether tumor-infiltrating CXCL17+ cells were an independent prognostic factor of survival and whether they were correlated with immune infiltration in HCC." (PMID 25303284, 2014). "Alternatively, CXCL17+ cells other than CXCL17− neutrophils may be specifically recruited to the tumor microenvironment." (PMID 25303284, 2014). "Further studies that define the potential regulatory role of CXCL17 in tumor-infiltrating neutrophils/macrophages in HCC may provide new insights into therapeutic strategies aimed at forming an effective immune response in HCC." (PMID 25303284, 2014). "Stromal cells with mononuclear morphology and tumor cells also produced CXCL17." (PMID 25303284, 2014). "Whether CXCL17 expression affects the metastatic potential of tumor cells is of immense interest in tumor biology." (PMID 22952881, 2012). "Herein, we have demonstrated the potential role of chemokine CXCL17 in tumor formation." (PMID 22952881, 2012).
tumor (continued). "Although the mechanism by which the CXCL17 gene is activated in malignant cells remains unknown, CXCL17 seems to be involved in the complex tumor microenvironment in some human cancers." (PMID 22952881, 2012). "Moreover, some human tumor cells expressed CXCL17, and a xenograft tumor model using SCID mice showed rapid tumor formation with rich microvasculature." (PMID 22952881, 2012). "We further addressed whether CXCL17-responding myeloid-derived cells could promote tumorigenesis of CXCL17-expressing tumor cells." (PMID 22952881, 2012). "Additionally, CXCL17 influences the tumor milieu by upregulating CCL20 expression in HGC27 cells." (PMID 41459506, 2025). "Furthermore, another chemokine, CXCL17, which was found to be upregulated in breast tissue, has been reported to be involved in angiogenesis, recruitment of immune suppressor cells and tumor metastasis." (PMID 31620367, 2019). "Interestingly, another study suggested that CXCL17 might be involved in anti-tumor immune response during pancreatic carcinogenesis." (PMID 25303284, 2014). "Therefore, CXCL17 expression in tumor-infiltrating neutrophils implies that CXCL17+ neutrophils might regulate neutrophil infiltration in an autocrine manner." (PMID 25303284, 2014). "Thus, CXCL17 might be responsible for neutrophil accumulation in tumor and contribute to the immunosuppressive microenvironment in the tumor." (PMID 25303284, 2014). "Therefore, we propose that the aberrant expression of CXCL17 in tumor cells may play a pivotal role in tumor progression." (PMID 22952881, 2012). "Interestingly, CXCL17-responding cells could also moderately promote tumor formation of the control LacZ-SW620 cells." (PMID 22952881, 2012). "VEGF-correlated chemokine-1 (VCC-1), also known as C-X-C motif chemokine ligand 17 (CXCL17), has been suggested to play a role in promoting tumor angiogenesis and metastasis." (PMID 39898238, 2025). "Silencing of CXCL17 has been shown to reduce GPR35 expression and inhibit tumor cell proliferation, supporting the therapeutic potential of targeting GPR35–CXCL17 axis." (PMID 41459506, 2025). "CXCL17 promotes the infiltration of CD4+ T cells and CD68+ immune cells into the tumor microenvironment, thereby accelerating tumor growth and metastasis." (PMID 41459506, 2025). "In a more detailed analysis, we found that among 28 subsets of tumor-infiltrating lymphocytes, 22 were correlated with CXCL2, 21 with CXCL12, 15 with CXCL14, and 19 with CXCL17." (PMID 38232115, 2024). "It proves its anti-tumor effect by inhibiting the cell cycle in the G2/M phase and decreasing the synthesis of mucin-1 (MUC1) and expression of C-X-C motif chemokine 17 (CXCL17), which stimulates the tumor microenvironment." (PMID 39339011, 2024). "For example, CXCL17 was reported to be highly expressed in breast cancer, hepatocellular cancer, and colon cancer, where it contributed to poor prognosis, whereas in pancreatic cancer it might exert a protective role through stimulating anti-tumor immune responses." (PMID 36614059, 2022). "Supporting this notion, we found TCh3 tumor expressed a higher level of CXCL17 and HNSCC patients with higher expression of CXCL17 exhibit a better prognosis." (PMID 35366939, 2022). "Measurements of CXCL16 and CXCL17 strengthen the prognostic value of LGR5 by detecting high number of aggressive tumor cells and/or tumor growth promoting cells in the tumor cell microenvironment." (PMID 35008827, 2021). "Our study indicates that decreases in MDSCs, induced by reductions in CXCL17 as a consequence of CCL17 levels, led to tumor suppression." (PMID 33670758, 2021). "While, a number of genes were observed to be down-regulated in HC including CXCL17, KRT19 and BPIFB1 which are known to be involved in anti-tumour immune reactions." (PMID 28330331, 2016). "Interestingly, CXCL17 may also be involved in anti-tumor immune response." (PMID 25303284, 2014).
tumor (continued). "Our data showed that CXCL17-expressing tumor cells increased immature CD11b+Gr1+ myeloid-derived cells at tumor sites in mice and promoted CD31+ tumor angiogenesis." (PMID 22952881, 2012). "Since it is well known that tumor-bearing conditions significantly increased the population number of CD11b+Gr-1+ myeloid-derived cells in the spleen of immune-competent mice, we further examined whether CXCL17 expression could increase the population number of CD11b+Gr-1+ myeloid-derived cells." (PMID 22952881, 2012). "In summary, these findings suggest that CXCL17 contributes to OSCC progression and poor prognosis by modulating systemic immune responses and reshaping the tumor immune microenvironment, highlighting its potential as both a prognostic biomarker and a therapeutic target." (PMID 42255223, 2026). "Still, it is noted that there is not much information about CXCL17, and morespecific research should be done to discover its receptor, which is stillundetermined, its physiological function, and even its role in tumor immunity." (PMID 41553842, 2026). "In this study, we also found that the CXCL17 showed higher expression level in all clusters than GTEx, and it interacted with other molecules in TME and promoted tumor growth and enhanced immune escape." (PMID 36765073, 2023). "The CXCL17 is highly expressed in various cancer cells and induces the expression of vascular endothelial growth factor (VEGF) in monocytes and endothelial cells, and promotes tumor growth by increasing angiogenesis and enhancing immune escape." (PMID 36765073, 2023). "Elevated CXCL17 expression has been observed in patients with both non-malignant and malignant diseases, where it is thought to directly promote tumor progression." (PMID 31357969, 2019). "Similarly, co-expression of Intercellular Adhesion Molecule-2 (ICAM-2) and chemokine C-X-C motif ligand 17 (CXCL17) elicits anti-tumor immune responses and suppresses tumor growth." (PMID 26697524, 2015). "APOC1 is primarily expressed in tumor cells and macrophages and shows a positive correlation with the expression of genes such as CD68, CD86, CD163, CXCL17, CXCL8, and IL-10, suggesting that APOC1 may promote tumor progression by influencing macrophage polarization." (PMID 39877420, 2024). "Therefore, the negative association between CXCL17 and CD4 cells also indicated the pro-tumor effect of CXCL17 in HCC." (PMID 25303284, 2014). "In comparison with naïve tumor-free mice, the population of CD11b+Gr-1+ cells could increase in the tumor-bearing mice, although the populations of CXCL17- and LacZ-Colon26 tumors were not segregated." (PMID 22952881, 2012). "CXCL17-expressing Colon26 cells could form tumors rapidly in vivo, and tumor growth between CXCL17- and LacZ-expressing Colon26 cells was not segregated." (PMID 22952881, 2012). "Moreover, CXCL17 and GPR35 might specifically identify less differentiated tumor cells." (PMID 35008827, 2021). "Furthermore, upregulated CXCL14/17 expression showed negative correlation with the abundance of three tumor-infiltrating lymphocytes (CXCL14: Tcm CD8, Act CD4, CD56dim; CXCL17: Tcm CD8, Act CD4, Tem CD4)." (PMID 38232115, 2024). "Moreover, regardless of tumor differentiation grade, tumor size, TNM stage, and aspartate transaminase (AST) and AFP levels, peritumoral CXCL17 was a good predictor of recurrence (all P<0.05)." (PMID 25303284, 2014).
cancer (30 papers, 2012 to 2026). A tumor composed of atypical neoplastic, often pleomorphic cells that invade other tissues. "In summary, knock down of CXCL17 in resistant cells caused T cell-sensitization and increased cancer cell cytotoxicity." (PMID 38654067, 2024). "CXCL17 plays a crucial part in angiogenesis, which is essential for supplying nutrients to cancer cells, encouraging cancer growth, and enabling invasion." (PMID 38384293, 2024). "Abnormal expression of CXCL17 in tumor cells can accumulate immature myeloid cells and promote cancer development by promoting vascular proliferation." (PMID 37889664, 2023). "CXCL17 can recruit monocytes, macrophages and mature and immature dendritic cells (DC), which is of great significance for the development of multiple cancer types." (PMID 37889664, 2023). "TCGA analysis identified that CXCL17 was negatively correlated with some cancer-promoting pathways and involved in inflammatory activities." (PMID 36614059, 2022). "For other chemokines, CXCL11 was positively related to approximately all other chemokines except CCL14, CCL15, CCL16, CCL27, CCL28, CXCL6, and CXCL17 in almost all types of cancers." (PMID 35935945, 2022). "We analyzed the mRNA levels of CXCL17 in a series of GC cell lines using the Cancer Cell Line Encyclopedia (CCLE) database." (PMID 36614059, 2022). "For instance, cancer cells with higher CXCL17 expression had a larger area of the dose response curve (AUC) of KW2449 and a smaller AUC of lapatinib." (PMID 36614059, 2022). "Increased expression of CXCL17 by PMN-MDSCs was also of interest, as previous studies have implicated CXCL17 in the recruitment of MDSCs and poor prognosis in human cancer patients." (PMID 30837603, 2019). "Our study provides novel therapeutic options to inhibit the metastatic niche, including the targeting of CXCL17 and mechanisms promoting cancer colonization activated by CD11b+Gr-1+ MDSC-derived PDGF-BB." (PMID 30755260, 2019). "CXCL17-induced CD11b+Gr-1+ MDSCs also supported cancer cell extravasation and survival in the lungs of mice." (PMID 30755260, 2019). "Mouse anti-Gr-1 antibody (0.25 mg/mouse, MDSC depletion) was administrated by IP every 4 days during CXCL17 pretreatment in mice prior to PKH26-labeled 4T1 cancer cell implantation by tail vein injection." (PMID 30755260, 2019). "Some of the identified factors (such as TSPAN8, CXCL17, CRIP2, STARD10, CSNK2A1) and pathways (i.e. apoptosis, TGFβ, VEGF and ERK signaling) are known to participate in cancer as well as their identification here linked with airway remodeling in mustard lung." (PMID 24978043, 2014). "The stimuli necessary to effect CXCL17 expression in some cancer cells and the manner in which these stimuli are involved in cancer progression remain to be elucidated." (PMID 22952881, 2012). "In our data, CXCL17 was expressed frequently in colorectal, breast, and lung (non-small cell type) cancer cell lines and some specimens from those patients." (PMID 22952881, 2012). "CXCL17- or LacZ-expressing murine Colon26 cancer cells were transplanted into the subcutaneous space of syngeneic BALB/c mice." (PMID 22952881, 2012). "We also performed GSEA hallmarks of cancer analysis on CXCL17." (PMID 36614059, 2022). "In addition, CXCL16 and CXCL17 have been reported to be positively correlated with M2-macrophage infiltration, enhanced angiogenesis, and poor prognosis in cancer." (PMID 34459571, 2021). "In addition, ectopic expression of CXCL17 increases tumorigenesis and cancer growth by recruitment of CD11b+Gr-1highF4/80− cells in the primary site of colon cancer." (PMID 30755260, 2019).